RN7SL738P (RNA, 7SL, cytoplasmic 738, pseudogene)
Gene: Miscellaneous RNA gene on chromosome 3 (196,399,911 to 196,400,207, forward strand). Ensembl gene ENSG00000243339.
Homologues: Orthologues: chimpanzee Metazoa_SRP (99% identical). Paralogues in human: RN7SL2 (81% identical), RN7SL1 (81% identical), RN7SL118P (79% identical), RN7SL126P (79% identical), RN7SL3 (79% identical), RN7SL45P (79% identical), RN7SL492P (79% identical), RN7SL680P (79% identical), RN7SL732P (79% identical), RN7SL336P (78% identical), RN7SL612P (78% identical), RN7SL769P (78% identical), and 704 more.